ZNF671 (zinc finger protein 671)
Description:
May be involved in transcriptional regulation.
Synonyms: FLJ23506
Tractability: PROTAC: ubiquitination databases record sites on it.
Gene: Protein-coding gene on chromosome 19 (57,719,751 to 57,727,624, reverse strand). Ensembl gene ENSG00000083814.
Subcellular location: Nucleus
Subcellular location (Human Protein Atlas): Nucleoplasm
Pathways (Reactome):
Gene expression (Transcription): Generic Transcription Pathway
Gene Ontology:
Molecular function: DNA-binding transcription factor activity; RNA polymerase II cis-regulatory region sequence-specific DNA binding
Biological process: regulation of transcription by RNA polymerase II; regulation of DNA-templated transcription
Cellular component: nucleoplasm; nucleus
Genetic constraint (gnomAD): Loss-of-function variants: 21 observed, 17.77 expected, observed/expected ratio (o/e) 1.18, 90% interval 0.84 to 1.68. The upper end of that interval is the gene's LOEUF score, 1.68, which puts it in group 6 of 6, group 1 being the genes least tolerant of losing a copy. Missense variants: 637 observed, 694.2 expected, observed/expected ratio (o/e) 0.92, 90% interval 0.86 to 0.98. Synonymous variants: 238 observed, 252.27 expected, observed/expected ratio (o/e) 0.94, 90% interval 0.85 to 1.05.
Homologues: Orthologues: chimpanzee ZNF671 (99% identical), macaque ZNF671 (94% identical), Drosophila melanogaster CG11902 (26% identical), zebrafish znf574 (23% identical), Drosophila melanogaster CG10631 (20% identical), Drosophila melanogaster CG11696 (18% identical). Paralogues in human: ZNF667 (37% identical), ZNF662 (29% identical), ZNF865 (27% identical), ZNF366 (20% identical), ZNF710 (19% identical), ZNF783 (13% identical), ZNF212 (12% identical).
Diseases named in the same sentence as ZNF671 in open-access papers:
ZNF671 is named in the same sentence as 36 diseases in open-access papers, as found by Europe PMC text mining. Sharing a sentence is not in itself a finding about the gene and the disease. The quoted sentences say what the papers report.
cervical carcinoma (10 papers, 2014 to 2026). A carcinoma arising from either the exocervical squamous epithelium or the endocervical glandular epithelium. "Recent studies have reported DNA methylation of ZNF671 in cervical cancer, nasopharyngeal carcinoma, colorectal carcinoma and many others." (PMID 39595048, 2024). "The positive expression rates of ZNF671 in cervical cancer and CIN3 were significantly higher than those in CIN1 (P = 0.000, 0.000)." (PMID 36803573, 2023). "The aim was to investigate the diagnostic value provided by methylation biomarkers of six tumor suppressor genes (ASTN1, DLX1, ITGA4, RXFP3, SOX17 and ZNF671) for cervical precancerous lesions and cervical cancer." (PMID 36803573, 2023). "In previous studies we have shown that hypermethylation of CpG islands in proximity to the genes DLX1, ITGA4, RXFP3, SOX17, and ZNF671 correlated with the presence of cervical precancerous lesions and cervical cancer." (PMID 30509219, 2018). "And 97.3% of cervical cancer patients showed ZNF671 DNA methylation." (PMID 36803573, 2023). "In this study, we found that the ZNF671 promoter is significantly methylated in 17 solid tumors, based on the TCGA datasets, which is consistent with studies in urothelial carcinoma, clear cell renal cell carcinomas, and cervical cancer." (PMID 31134149, 2019). "One identified target, the ZNF671 transcriptional repressor (arrow head), caught our attention, as ZNF671 was recently found epigenetically silenced by promoter DNA methylation in renal cell and cervical cancers." (PMID 26320192, 2015). "As the degree of cervical lesions rises, the positive methylation rate of ZNF671 reached 30.3% in CIN2, 71.0% in CIN3 and 97.3% in cervical cancer." (PMID 36803573, 2023). "ZNF671, a member of the KRAB-ZF family, is silenced by promoter methylation in renal cell, cervical carcinoma and urothelial carcinoma." (PMID 29052525, 2017). "A methylation signature comprising the 5′ regions of the genes DLX1, ITGA4, RXFP3, SOX17 and ZNF671 specific for CIN3 and cervical cancer (termed CIN3+) was identified and validated." (PMID 24647315, 2014). "In cervical cancer a DNA hypermethylation marker panel consisting of the six marker regions ASTN1, DLX1, ITGA4, RXFP3, SOX17, and ZNF671 may be a useful tool for triaging HPV-positive women." (PMID 30509219, 2018). "Although ZNF671 was previously found to be silenced by promoter methylation in renal cell and cervical carcinomas, its role in UC has never been explored." (PMID 26320192, 2015). "DNA isolated from 49 tissue samples with no histological evidence for CIN (normal), from 43 samples diagnosed as CIN3 and from 54 cervical cancer tissues was bisulfite-treated and used in qMSP experiments for the five marker regions DLX1, ITGA4, RXFP3, SOX17, and ZNF671." (PMID 24647315, 2014).
breast carcinoma (5 papers, 2015 to 2024). "Western blot and transwell assays identified that ZNF671 inhibited epithelial-mesenchymal transition, migration, and invasion of central nervous system cancers, lung cancer, melanoma, and breast carcinoma in vitro." (PMID 32796700, 2020). "Results from single cell RNA seq experiments (scRNA) also indicated that ZNF671 inhibited EMT, migration, and invasion of CNS cancers, lung cancer, melanoma, and breast carcinoma in vitro." (PMID 39595048, 2024). "Overexpression of ZNF671 inhibited EMT, migration, and invasion of CNS cancers, lung cancer, melanoma, and breast carcinoma in vitro." (PMID 34439859, 2021). "Western blot and transwell assays identified that ZNF671 inhibited EMT, migration, and invasion of CNS cancers, lung cancer, melanoma, and breast carcinoma in vitro." (PMID 31781507, 2019). "Second, we found the ZNF671 inhibits angiogenesis, apoptosis, EMT, hypoxia, invasion, and quiescence in CNS cancers, lung cancer, melanoma, and breast carcinoma." (PMID 31781507, 2019). "Western blot and transwell assays showed that ZNF671 inhibited EMT, migration, and invasion of CNS cancers, lung cancer, melanoma, and breast carcinoma in vitro." (PMID 31781507, 2019). "Based on this reasoning, we selected ZNF671 and TENC1 promoter methylation as putative markers of Epi‐Basal breast cancers from the top promoter methylation events identified as significantly associated with tumors classified as Epi‐Basal." (PMID 25468711, 2015).
lung carcinoma (5 papers, 2019 to 2024). "ZNF671 can suppress the growth and spread of lung cancer by inhibiting the Wnt/β-catenin signaling pathway." (PMID 37622116, 2023).
urothelial carcinoma (5 papers, 2015 to 2024). A malignant neoplasm derived from the transitional epithelium of the urinary tract (urinary bladder, ureter, urethra, or renal pelvis). "In urothelial carcinoma (UC) cells, ZNF671 re-expression inhibited tumor growth and invasion, in conjunction with downregulation of cancer stem cell markers (c-KIT, NANOG, OCT4)." (PMID 39595048, 2024). "Our results demonstrate that ZNF671 promoter methylation is frequently found in urothelial carcinoma and thus, represents a promising, non-invasive biomarker for the detection and guided therapy of urothelial carcinoma." (PMID 26320192, 2015). "Taken together, these results demonstrate that the zinc-finger protein gene, ZNF671, is epigenetically silenced in human urothelial carcinoma." (PMID 26320192, 2015).
cervical squamous cell carcinoma (4 papers, 2019 to 2024). A squamous cell carcinoma arising from the cervical epithelium. "Survival analysis established that the downregulation of ZNF671 predicted poor prognosis in cervical squamous cell carcinoma." (PMID 36803573, 2023).
CNS cancers (4 papers, 2019 to 2024). "In glioma (brain), ZNF671 expression was negatively correlated with angiogenesis in MUV1, with DNA repair, DNA damage, and cell cycle in MUV5, with DNA repair in BCH836, and with apoptosis in BCH869." (PMID 31781507, 2019). "Our findings revealed that ZNF671 is a tumor suppressor in LUAD, BRCA, GBM, glioma, AST, ODG, and MEL." (PMID 31781507, 2019). "In this study, we found a total of eight solid tumor-related ZNF671 scRNA-seq datasets, including GBM, glioma, AST, ODG, LUAD, MEL, and BRCA." (PMID 31781507, 2019). "ZNF671 expression was positively correlated with hypoxia in MUV10, BCH836, and BCH869 in glioma (brain)." (PMID 31781507, 2019). "Expression analysis showed that ZNF671 was obviously downregulated in GBM, glioma, AST, ODG, LUAD, MEL, and BRCA, which indicated that ZNF671 might play an important role in tumor progression." (PMID 31781507, 2019). "In glioma (PDX), ZNF671 expression in BCH869 correlated negatively not only with hypoxia but also with EMT, apoptosis, angiogenesis, and quiescence." (PMID 31781507, 2019).
nasopharyngeal carcinoma (4 papers, 2017 to 2024). A carcinoma arising from the nasopharyngeal epithelium. "Our previous studies demonstrated that ZNF671 is a tumor suppressor that is epigenetically silenced by DNA methylation in nasopharyngeal carcinoma, BRCA, CESC, HNSC, KIRP, LUAD, PAAD, and UCEC." (PMID 31781507, 2019). "Our previous studies demonstrated that ZNF671 is a tumor suppressor that is epigenetically silenced by DNA methylation in nasopharyngeal carcinoma, but there is limited information regarding the role of ZNF671 methylation among different solid cancer types." (PMID 31134149, 2019).
colorectal cancer (3 papers, 2024 to 2026). A primary or metastatic malignant neoplasm that affects the colon or rectum. "In contrast, zinc finger protein 671 (ZNF671) is negatively correlated with Notch signaling in colorectal cancer." (PMID 41602823, 2026). "Zinc finger protein 671 plays a tumor suppressor role in colorectal cancer by inhibiting Notch signaling pathway." (PMID 39717098, 2024). "Up-regulation of ZNF671 in colorectal carcinoma (CRC) cells resulted in suppressive effects on proliferative ability and metastatic potency via the deactivation of Notch signaling, with decreases in expression of Notch1, NICD, HES1 and HEY1." (PMID 39595048, 2024).
oral cancer (3 papers, 2015 to 2024). "Over-expression of ZNF671 in UM-SCC-1 oral cancer cells resulted in a significant reduction in tumor cell mobility and invasion compared to the empty-vector control cells." (PMID 39595048, 2024). "In order to investigate potential tumor suppressive properties of ZNF671 in HNSCC cells, we overexpressed ZNF671 in the oral cancer cell line UM-SCC-1 by lentiviral transduction." (PMID 39595048, 2024). "We have expressed another KRAB-ZNF protein (ZNF671) in UM-SCC-1 cells, but also found it was not possible to express ZNF671 protein within other oral cancer cell lines such as SCC-25 and SCC-15 (data not shown)." (PMID 37254212, 2023).
ovarian carcinoma (2 papers, 2020 to 2023). A malignant neoplasm originating from the surface ovarian epithelium. "Previous studies have demonstrated that ZNF671 is associated with a poorer prognosis of ovarian cancer patients." (PMID 37215982, 2023). "Previous studies have shown that the hypermethylation level of ZNF671 is closely related to serous recurrence of ovarian cancer." (PMID 37215982, 2023). "Also, the methylation status of ZNF671 was utilized as an independent marker for predicting ovarian cancer recurrence." (PMID 31894857, 2020).
bladder cancer (1 paper, 2024). "In this study, we initially utilized the TCGA bladder cancer cohort to investigate potential DNA methylation markers associated with BCa in the ZNF671, OTX1, and IRF8 genes." (PMID 38472940, 2024). "Notably, the hypermethylated ZNF671 marker holds considerable promise in distinguishing between bladder cancer and non-BCa urine samples by the tree structure, achieving a 92.7% probability." (PMID 38472940, 2024).
bladder urothelial carcinoma (1 paper, 2015). "In conclusion, ZNF671 is a potential tumor suppressor that is epigenetically silenced by promoter methylation in bladder urothelial carcinoma." (PMID 26320192, 2015).
cervical intraepithelial neoplasia (1 paper, 2025). "A panel of six methylation markers (ASTN1, DLX1, ITGA4, RXFP3, SOX17, ZNF671; GynTect® assay) has shown promise in diagnosing cervical intraepithelial neoplasia (CIN)." (PMID 40022051, 2025).
colon adenocarcinoma (1 paper, 2021). "A cluster of 13 CpG loci (11 genes) were identified that displayed differential methylation in colon adenocarcinoma (COAD) (N = 289) compared to normal colon tissues (N = 38): ZNF671, TWIST1 (two CpG loci), TMEFF2, TM6SF1, GAS7, MAL, HIN1 (two CpG loci; SCGB3A1), COL6A2, AKR1B1, GPX7, ARHGEF7)." (PMID 34903270, 2021).
dysplasia (1 paper, 2025). A usually neoplastic transformation of the cell, associated with altered architectural tissue patterns. "Five of the six markers (ASTN1, ITGA4, RXFP3, SOX17, and ZNF671) showed good positivity in vulvar dysplasia but with unexpected high positivity in VLSIL (VIN I) FFPE samples compared to higher dysplasia grades." (PMID 40022051, 2025).
head and neck cancer (1 paper, 2024). A primary or metastatic malignant neoplasm affecting the head and neck. "Our original DNA methylation profiling of head and neck cancers demonstrated that ZNF671 showed elevated DNA hypermethylation as well as reduced gene expression in most head and neck primary tumors." (PMID 39595048, 2024).
non-small cell lung carcinoma (1 paper, 2023). A group of at least three distinct histological types of lung cancer, including non-small cell squamous cell carcinoma, adenocarcinoma, and large cell carcinoma. "Recent studies have found that the expression level of ZNF671 in non-small cell lung cancer is associated with an increased risk of disease progression and metastasis." (PMID 37622116, 2023).
sarcoma (1 paper, 2019). A usually aggressive malignant neoplasm of the soft tissue or bone. "ZNF671 protein expression was low and/or absent in only 41.7 and 45.4% of colorectal and stomach cancers, respectively, and the protein expression of ZNF671 in sarcoma was unclear." (PMID 31134149, 2019).
serous ovarian carcinoma (1 paper, 2019). "Another recent study has highlighted the tumor suppressor role of ZNF671 and its methylation could act as a predictor for early recurrence of serous ovarian carcinoma." (PMID 31608277, 2019).
tongue SCC (1 paper, 2024). "Similarly, ZNF671-initiated downregulation of ATF3 is consistent with its role as a negative regulator in the growth and migration of human tongue SCC cells in vitro." (PMID 39595048, 2024).
tumor (19 papers, 2015 to 2025). "Functional assays and prognostic analysis found that high ZNF671 expression suppressed tumor cell proliferation, migration, and invasion, and downregulation of ZNF671 was associated with poor clinical prognosis in BRCA, CESC, HNSC, KIRP, LUAD, PAAD, and UCEC." (PMID 31134149, 2019). "Clinically, high ZNF671 methylation in UC tumor tissues (n=96; 63 bladder, 33 upper urinary tract) associated with tumor grade and poor locoregional disease-free survival." (PMID 26320192, 2015). "Based on our observed relationship between increased ZNF671 hyper-methylation and tumor grade, we examined possible association of ZNF671 methylation levels with UC tumor recurrence, showing that ZNF671 methylation was significantly higher in relapsed tumor tissue samples." (PMID 26320192, 2015). "We also observed ZNF671 epigenetic repression in patient tumors of the upper urinary tract, which in Taiwan is a more common site for this malignancy, in addition to significant association with high tumor grade and shorter locoregional disease-free survival." (PMID 26320192, 2015). "Based on the TCGA database, we found that high methylation of ZNF132 and ZNF671 results in gene silencing or reduced expression, which in turn influences the tumor progression and correlates with the prognosis of CRC patients." (PMID 40791581, 2025). "Previous studies, including our own, have revealed that ZNF671 exhibits tumor suppressor properties." (PMID 38472940, 2024). "Previous studies have shown that ZNF671 is a tumor suppressor gene that is silenced by epigenetic modifications." (PMID 37622116, 2023). "The results unfolded that the tumor volume and weight were deceased in the ZNF671 overexpression group." (PMID 37215982, 2023). "Increasing studies have shown that ZNF671, as a tumor suppressor, is epigenetically inhibited by DNA methylation in a variety of tumors 13-15." (PMID 37215982, 2023). "Then we analyzed the TCGA LUAD dataset, which showed that ZNF671 was downregulated in tumor tissues compared to normal tissues, with statistical differences, but the difference was not significant (p=0.04)." (PMID 37622116, 2023). "It has been confirmed that ZNF671 functions as a tumor suppressor in multiple carcinomas via DNA methylation." (PMID 35164660, 2022). "BLU and ZNF671, two genes which are thought to act as tumour suppressors in other cancer types, have significantly higher methylation in chemoresistant HGSOC tumour samples." (PMID 34885103, 2021). "Overexpression of ZNF671 suppressed the proliferation and migratory and invasive abilities of the tumor cells as determined by Transwell migration and invasion assays." (PMID 31134149, 2019). "The heterogeneous functional states of cell subgroups and correlation analysis showed that ZNF671 played tumor suppressor roles in heterogeneous cancer cell populations." (PMID 31781507, 2019). "We performed a pan-cancer analysis of the protein expression of ZNF671 using the HPA, which presented the protein expression of ZNF671 in 17 different tumor types." (PMID 31134149, 2019). "Our results provide important insights into tumor heterogeneity and enhance knowledge of the tumor suppressor role of ZNF671 in solid tumors." (PMID 31781507, 2019). "In conclusion, this study systematically evaluated the tumor suppressor role of ZNF671 based on scRNA-seq datasets." (PMID 31781507, 2019). "Recent studies have demonstrated that ZNF671 is epigenetically silenced by DNA methylation and functions as a tumor suppressor in multiple carcinomas." (PMID 29052525, 2017). "Taken together, these results suggest that ZNF671 is epigenetically silenced by promoter methylation, with progressively increased methylation positively correlating with increased UC patient tumor grade." (PMID 26320192, 2015). "Based on our cell culture findings, we next examined the tumor suppressive effects of ZNF671 in an in vivo xenograft mouse model." (PMID 26320192, 2015).